POSTN (periostin)
Diseases named in the same sentence as POSTN in open-access papers (continued):
Sharing a sentence is not in itself a finding about the gene and the disease.
ovarian carcinoma (continued). "It has been recently shown that POSTN may support adhesion and migration of ovarian epithelial cancer cells by interacting with αvβ3 and αvβ5 integrins." (PMID 35163164, 2022). "Moreover, periostin expression by ovarian cancer cells was induced by TGF-β from infiltrating macrophages, which in turn promoted their skewing towards the M2 phenotype." (PMID 33466303, 2021). "In ovarian cancer, the expression of periostin promotes tumor infiltration with macrophages." (PMID 33466303, 2021). "Moreover, some studies indicate that periostin, together with several other ECM proteins, is associated with drug resistance in ovarian cancer cell lines." (PMID 31936272, 2020). "Some data indicate that periostin may exert an important role in ovarian cancer and may be potentially useful as a prognostic and predictive biomarker." (PMID 31936272, 2020). "The results of our study add to some previous observations that fibronectin and periostin may have prognostic significance in ovarian cancer." (PMID 31936272, 2020). "Interestingly, the neutralizing antibody to periostin, MZ-1, suppressed tumor metastasis of periostin overexpressing ovarian cancer cell line by intra-peritoneal injection." (PMID 29758011, 2018). "However, the role of periostin in metastasis of various tumors remains conflicted: it appears to play a positive role in metastasis of colon and ovarian cancers but suppresses metastasis in lung and bladder cancers." (PMID 29163770, 2017). "For instance, VCAN and POSTN were demonstrated in vitro to be involved in ovarian cancer invasion induced by TGF-β signaling, and COL11A1 was shown to increase continuously during ovarian cancer progression and to be highly overexpressed in recurrent metastases." (PMID 27843486, 2016). "EOC cells can secret POSTN and accumulate in malignant ascites of ovarian cancer patients." (PMID 26716408, 2016). "Furthermore, we found higher periostin levels in the supernatants of six myeloma cell lines in comparison with four ovarian cancer cell lines." (PMID 27716740, 2016). "Moreover, recombinant purified POSTN supports the adhesion and migration of ovarian epithelial cancer cells by interacting with integrin receptors αVβ3 and αVβ5." (PMID 26716408, 2016). "The periostin levels in the supernatants of the myeloma cell lines were higher comapred with those found in the supernatants of the ovarian cancer cell lines (mean±s.d.: 17.2±6.14 vs 2.98±1.92 ng/ml; P=0.001; levels of periostin in the RPMI+FBS was 0.595 ng/ml)." (PMID 27716740, 2016). "Initial evidence for a possible role of LPA and its receptors in EMT was derived from experiments in hepatocellular carcinoma and ovarian cancer by showing a proline-rich tyrosine kinase 2 (PYK2) or periostin (alias osteoblast-specific factor-2)-induced EMT, upon LPA treatment." (PMID 25209561, 2015). "Those genes might be used as biomarkers for the ovarian cancer EMT-related process, especially, the strong different expression of periostin from stage III to IV which may indicate the ovarian cancer EMT process." (PMID 26099468, 2015). "Therefore, although ovarian cancer cells have the ability to adhere to both periostin and TGFBI, they likely utilize distinct mechanisms." (PMID 22640878, 2012). "Since these results seem to be cell-type and system specific, we attempted to extend a similar analysis with respect to ovarian cancer cells, including the comparison to its paralogue, periostin, which has been suggested to have a proactive role in ovarian cancer migration." (PMID 22640878, 2012). "We first compared the functions of TGFBI and periostin on ovarian cancer cells." (PMID 22640878, 2012). "Intense POSTN expression was also observed in the stroma of ovarian carcinoma, as well as in lung and colon carcinoma where it was concentrated at the interface between the tumor epithelial cells and the stromal compartment that presented a robust inflammatory reaction (respectively)." (PMID 21611158, 2011).
ovarian carcinoma (continued). "Additionally, POSTN-induced NF-κB activation stimulates the production of TGF-β2, which drives the differentiation of adipose-derived stromal cells into cancer-associated fibroblasts (CAFs)—another key player in ovarian cancer progression." (PMID 40330466, 2025). "Thus, DDR2 expression in CAFs regulates the steps of ovarian cancer metastasis through periostin." (PMID 35884543, 2022). "Therefore, POSTN could be a useful prognosis marker and therapeutic target for epithelial ovarian cancer." (PMID 36550569, 2022). "Although the role of POSTN in regulating TAMs or CAFs has been discussed, the interplay among ovarian cancer, TAMs and CAFs in ovarian cancer progression, as well as the signaling pathway(s) that cancer-cell-derived POSTN regulates in ovarian cancer is still unknown." (PMID 36550569, 2022). "Interestingly, according to the expression profiling based on the parabiosis model of ovarian cancer hematogenous metastasis, four genes (POSTN, LUM, COL3A1, COL5A2) of the LMGS were shown to be significantly up-regulated in the omental metastases generated through a hematogenous route." (PMID 31888563, 2019). "Therefore, evaluating the mechanism of TGFBI and periostin function in ovarian cancer cells may shed light on their relationship and function during ovarian carcinogenesis." (PMID 22640878, 2012). "Although this contradicts recent evidence that suggests periostin primarily interacts with ovarian cancer cells via an αvß3 integrin-dependent mechanism, it also suggests a delicate balance may exist between different integrin receptors on the cell surface that dictate specificity to the ECM." (PMID 22640878, 2012). "When binding to integrin αVβ3, CAF-derived POSTN can activate PI3K/AKT signalling pathway, promoting EMT, migration and invasion of ovarian cancers and EAC." (PMID 39780187, 2025). "Periostin-rich matrices—induced through integrin/NF-κB and TGF-β2 signaling—track with macrophage recruitment and fibroblast activation in ovarian cancer and can serve as desmoplastic sentinels measurable on archival formalin-fixed tissue." (PMID 41181126, 2025). "In EAC and ovarian cancer, CAF-derived POSTN acts as a ligand for integrins, activates the PI3K/Akt pathway, and induces the EMT, providing the impetus for cancer cell migration and invasion." (PMID 37143134, 2023). "CAFs enhance ovarian cancer invasion and metastasis through DDR2-regulated periostin 27 and promote colorectal cancer metastasis through IL-6-mediated LRG1 upregulation." (PMID 37056933, 2023). "POSTN+ CAFs are also related to poor prognosis in PDAC, CRC, NSCLC, EAC, gastric cancer, and ovarian cancer." (PMID 37143134, 2023). "HGSOC cells can recruit CD163+ TAMs through the release of periostin (POSTN), which is an ECM protein found to be elevated in ovarian cancer ascites." (PMID 35574025, 2022). "CAFs-derived POSTN activates fibroblasts through TGF-β1 and exerts effects on the migration and invasiveness of ovarian cancer via activating the PI3K/Akt pathway." (PMID 35681617, 2022). "POSTN can activate PI3K/AKT pathway to promote the proliferation and migration of ovarian cancer cells." (PMID 35813831, 2022). "DDR2 and POSTN signal through the PI3K/AKT and Src pathway and represent therapeutic targets in ovarian cancer." (PMID 35884543, 2022). "However, the upstream regulatory network of POSTN in ovarian cancer is largely unknown." (PMID 35884543, 2022). "The present study was aimed to validate two proteins, namely fibronectin (FN1) and periostin (POSTN), in the independent set of ovarian cancer samples." (PMID 31936272, 2020). "Eventually, the presence of OSF-2 with a molecular mass of 85–95 kDa and 170 kDa was also observed in cell culture medium of periostin-transfected SKOV-3—the ovarian adenocarcinoma cell line, and C848—the primary ovarian cancer cell line." (PMID 31412536, 2019). "POSTN induced EMT to promote the migration and invasion of ovarian cancer cells." (PMID 38280891, 2024).
ovarian carcinoma (continued). "Our data showing the connection between periostin-high expression in the TME in ovarian cancer and AKT activity support that targeting the AKT pathway could be a helpful strategy to treat OC patients with higher levels of periostin expression." (PMID 38049490, 2023). "POSTN upregulation has been demonstrated for many cancer types, such as non-small cell lung cancer (NSCLC), invasive ductal breast cancer (IDC), pancreatic, and ovarian cancer, and is consequently defined as a tumor-enhancing factor." (PMID 35163164, 2022). "POSTN-induced by TGF-β1 in fibroblasts led to the migration and invasion of ovarian cancer cells." (PMID 35800890, 2022). "At present, several biomarkers of ovarian cancer have been found, such as COL11A1 and POSTN." (PMID 35813831, 2022). "We created stable periostin expression in the ovarian cancer cell line OVCAR3 as well as the non-malignant Chinese hamster ovary (CHO) cell lines Pro5 (parental) and Lec4 (lacking GnT-V expression) to allow expression under adherent growth conditions." (PMID 30911061, 2019). "We found high levels of periostin in the supernatants of myeloma cell lines compared with ovarian cancer cell lines that were not influenced by the incubation with the stromal cell line HS5." (PMID 27716740, 2016). "However, in this study, tissue microarray contained different subtypes of epithelial ovarian cancer and borderline tumor and cannot distinguish which subtype of EOC is more correlated to POSTN expression due to limited numbers in different subtypes." (PMID 26716408, 2016). "Our analysis reveals a similar relationship between periostin (POSTN) and EMT of ovarian cancer." (PMID 26099468, 2015). "Especially, the strong different expression of POSTN and SMAD4 from stage III to IV may mark the ovarian cancer metastasis process." (PMID 26486520, 2015). "To evaluate the involvement of POSTN in modulating CAF activation, we surveyed the expression levels of CAF markers such as alpha smooth muscle actin (α-SMA) and fibroblast activation protein alpha (FAP) in the POSTN-high and POSTN-low ovarian cancer patients from the TCGA database." (PMID 36550569, 2022). "In the ovarian cancer study, the ES-2 cell line growing on OSF-2/fibronectin-coated dishes was much more resistant to PAC and carboplatin than cells growing on plates coated with fibronectin alone, indicating that extracellular periostin can promote drug resistance in vitro." (PMID 31412536, 2019). "The results showed that POSTN induced TGF-β2, but not TGF-β1, mRNA and protein expression in ovarian cancer cells." (PMID 36550569, 2022). "In contrast to TGFBI, the carboxy-terminus of periostin, lacking a RGD motif, is unable to support adhesion of ovarian cancer cells." (PMID 22640878, 2012). "Unlike most of the published reports showing that POSTN is produced by tumor stroma cells such as CAFs to exert its effect, we have unveiled an autocrine effect of POSTN triggering integrin dependent activation of IKKβ-mediated NF-κB and TGF-β2 in ovarian cancer cells." (PMID 36550569, 2022).
glioma (80 papers, 2008 to 2025). A benign or malignant brain and spinal cord tumor that arises from glial cells (astrocytes, oligodendrocytes, ependymal cells). "The POSTN-encoded protein in gliomas serves as an inducer of M2 macrophage recruitment, thereby inducing an immune-suppressive TME and facilitating the proliferation of glioma cells." (PMID 39574472, 2024). "Among the most significantly enriched transcripts after radiation exposure in HMVEC-derived EVs, we focused on POSTN, a matricellular protein that has been associated with glioma progression, particularly with glioma angiogenesis." (PMID 38347567, 2024). "Recently, it has been demonstrated that GSCs secrete POSTN to recruit tumor-associated macrophages (TAMs) whose density directly correlates with glioma grade, suggesting a supportive role for TAMs in tumor progression." (PMID 38347567, 2024). "The gene POSTN encodes the matricellular protein periostin, which is associated with glioma progression." (PMID 39126040, 2024). "Periostin (POSTN) is a tumor-associated macrophages (TAM) attractant that is preferentially secreted by glioma stem cells (GSCs)." (PMID 37274252, 2023). "The expression of periostin in pericytes was associated with angiogenesis in central nervous system tumors." (PMID 35056404, 2022). "Researchers have reported that POSTN functions as a progression-associated and prognostic biomarker in glioma via the induction of invasive and proliferative phenotypes." (PMID 34133324, 2021). "In the CGGA external validation, ABCC3 and POSTN were significantly associated with the OS in almost all the grades of primary and recurrent glioma." (PMID 32725165, 2020). "As for these 11 prognostic SRGs, ABCC3 and POSTN were significantly associated with almost all subtypes of glioma." (PMID 32725165, 2020). "Pro-invasive phenotypes of TW over-expressing glioma cells are associated with increased POSTN expression, increased adhesion to fibronectin (FN), alterations in F-actin organization and increased phospho-FAK expression." (PMID 31540485, 2019). "Consistent with the observation in normal mouse cells that TW is a direct transcriptional regulator of POSTN changes in POSTN expression are directly related to TW in gain and loss of function in glioma cells." (PMID 31540485, 2019). "It has also been reported that POSTN recruits M2 tumor-associated macrophages and promotes glioma stem cells (GSCs) growth." (PMID 31379707, 2019). "In both cell lines, TW loss of function mitigated glioma cell tumorigenicity with concurrent inhibition of periostin (POSTN) expression and PI3K/AKT signaling." (PMID 29754406, 2018). "In glioblastoma, glioma stem cells secret POSTN that contribute to recruit tumor-associated macrophages (M2)." (PMID 29946533, 2018). "Periostin (POSTN) is secreted by glioma stem cells, recruiting tumor‐associated macrophages that enhance tumor growth." (PMID 27888226, 2016). "Interestingly, among the transcripts down-regulated in DUSP8-GFP GdEC#1 and up-regulated in sh-DUSP8-GFP GdEC#1 we found POSTN, a matricellular protein that has been associated with glioma progression, particularly with glioma angiogenesis." (PMID 41029387, 2025). "Periostin was previously associated with prognosis and performance status in gliomas." (PMID 35387112, 2022). "POSTN gene encodes for periostin; an extracellular protein secreted by glioma cancer stem cells that recruits macrophages to the CSC niche, promotes angiogenesis (in part by increasing HIF-1α expression), cell invasion and glioblastoma progression in mouse models." (PMID 28472177, 2017). "In addition, survival analysis revealed that high POSTN expression was associated with poor prognosis in glioma patients, suggesting that POSTN may play a protumor role in GBM." (PMID 39227950, 2024). "Therefore, the interplay between glioma stem cells and tumor-associated macrophages can be modulated by POSTN and may be critical to promote glioblastoma tumor growth." (PMID 29946533, 2018).
glioma (continued). "Glioma stem cells (GSCs) secrete periostin (POSTN), a protein primarily found in the perivascular zone, and recruit GAMs through integrin αvβ3 to promote tumor progression." (PMID 40548122, 2025). "Multivariate Cox regression analysis indicated that POSTN and CHI3L1 were positively associated with poor prognosis of gliomas." (PMID 39574472, 2024). "For instance, in mouse xenograft models of human glioma, high POSTN mediated enhanced expression of TGFB1 and HIF1 alpha, which resulted in acquired resistance to anti-VEGF-A therapy." (PMID 38942020, 2024). "POSTN expression was significantly increased (p < 0.0001) in glioma tissues compared with normal brain tissues and was highest in GBM among the glioma types." (PMID 39227950, 2024). "CLOCK-BMAL1 complex in glioma stem cells leads to the upregulation of periostin (POSTN) that ultimately activates the TANK-binding kinase 1 (TBK1) in endothelial cells." (PMID 38994360, 2024). "In this study, immunohistochemical, immunoblotting and PCR analyses of normal brain tissue and glioma tissue confirmed that the expression of POSTN was significantly greater in glioma tissues than in normal brain tissues." (PMID 39227950, 2024). "Periostin expression levels directly correlate with tumor grade and recurrence in all grades of adult human glioma." (PMID 38969910, 2024). "The production of periostin by glioma stem cells has been identified as a key factor in promoting extravasation and migration of peripheral monocytes and M2-like TAMs in the glioma environment." (PMID 39033204, 2024). "To assess the potential clinical significance of POSTN, we examined the expression of POSTN in normal brain and glioma tissues through immunohistochemistry, quantitative real-time PCR (qRT‒PCR) and immunoblotting." (PMID 39227950, 2024). "The effect of major ECM proteins such as hyaluronic acid (HA), collagen, tenascin C (TNC), periostin, fibronectin, and laminin on immune landscape in glioma is presented." (PMID 38969910, 2024). "In GBM, periostin expression has been reported in both glioma stem cells and pericytes localized in the perivascular niches." (PMID 38969910, 2024). "Silencing of POSTN in cultured pericytes results in a reduction of angiogenic capacity, confirming the pivotal role of this extracellular matrix protein in glioma angiogenesis." (PMID 38347567, 2024). "This complex interplay between glioma cells, periostin, monocytes, TAMs, and various signaling molecules highlights the importance of understanding the molecular mechanisms governing glioma progression and potential targets for therapeutic intervention." (PMID 39033204, 2024). "Recently, miR-599 has been described as inhibitor of periostin expression and then as potential target to inhibit glioma cell motility and invasion." (PMID 38969910, 2024). "Beside the well-recognized role in glioma cancer cells behavior, periostin also plays a role in angiogenesis and immune evasion." (PMID 38969910, 2024). "It was shown that periostin expression in gliomas is related to neo-angiogenesis, and the expression is most significant in gliomas with microvascular proliferation (glioblastoma)." (PMID 39126040, 2024). "The expression levels of POSTN are relative to glioma grade progression and are inversely correlated with overall survival in high-grade glioma patients." (PMID 36980765, 2023). "POSTN was reported to enhance the resistance of glioma stem cells to anti-angiogenic therapy by positively regulating VEGFA expression through activation of STAT3." (PMID 37461041, 2023). "In glioma tissues from the high-risk group of the training cohort, HOXA5, PTPN2, WT1, HOXD10, POSTN, ADAMDEC1 and MYBPH were highly expressed." (PMID 37812190, 2023). "Nevertheless, HOXA5, PTPN2, WT1, HOXD10, POSTN, ADAMDEC1 and MYBPH were overexpressed in ATRX-mt glioma tissues with high-risk scores compared with low-risk scores." (PMID 37812190, 2023).